SHCBP1 (SHC binding and spindle associated 1)
Diseases named in the same sentence as SHCBP1 in open-access papers (continued):
Sharing a sentence is not in itself a finding about the gene and the disease.
lung carcinoma (7 papers, 2020 to 2025). "In lung cancer, SHCBP1 also interacts with FGF13 to downregulate p21/p27, thereby allowing cells to bypass the G1 checkpoint." (PMID 41009347, 2025). "In lung cancer, SHCBP1 silencing induces caspase-3 activation through PTEN upregulation and suppresses Wnt/β-catenin-mediated survival signaling." (PMID 41009347, 2025). "In lung cancer, SHCBP1 downregulates PTEN and inhibits caspase-3 activity, thereby suppressing intrinsic apoptosis." (PMID 41009347, 2025). "The mechanisms by which SHCBP1 regulates lung cancer progression were also elucidated by some researchers." (PMID 40799237, 2025). "For example, ICG-001 substantially inhibited EGF or SHCBP1-mediated CBP/β-catenin interaction in lung cancer." (PMID 41009347, 2025). "In lung cancer, SHCBP1 promotes cisplatin-induced apoptosis resistance, migration, and entry through activation of the Wnt pathway." (PMID 32370309, 2020). "SHCBP1 levels in non-small cell lung cancer were inversely correlated with survival, demonstrating the potential of SHCBP1 as a prognostic biomarker in lung cancer." (PMID 32370309, 2020). "Additionally, SHCBP1 depletion potentiated the sensitivity of lung cancer cells to low dose genotoxic agents, such as cisplatin, etoposide, and radiation, by facilitating mitotic catastrophe through G2/M checkpoint abrogation." (PMID 41009347, 2025). "Similarly, in lung cancer, SHCBP1 promotes migration and invasion and confers resistance to cisplatin-induced apoptosis through Wnt pathway activation." (PMID 40799237, 2025). "SHCBP1 is upregulated in lung cancer cell lines and plays a role in apoptosis." (PMID 32370309, 2020). "In addition, lung cancer patients with high SHCBP1 had poor prognosis." (PMID 34806315, 2022). "In lung cancer, EGF-induced nuclear translocation of SHCBP1 enhances β-catenin transactivation, increasing cellular stemness in non-small cell lung cancer (NSCLC)." (PMID 40799237, 2025). "In lung cancer, including NSCLC and small cell lung cancer (SCLC), SHCBP1 is identified as a key component within gene networks implicated in brain metastasis, immune evasion, and metabolic regulation." (PMID 41009347, 2025). "SHCBP1 also fosters cisplatin resistance through activation of Wnt/β-catenin signaling in head-and-neck squamous cell carcinoma (HNSCC) and lung cancer." (PMID 41009347, 2025). "To understand why SHCBP1 was closely correlated with tumour proliferation, we first assessed its expression in human-derived cell lines, including immortalized bronchial epithelial (HBE), lung cancer (A549, NCI-H1299, NCI-H460, NCI-H292), HeLa, and 293wt cells." (PMID 38365687, 2024). "Results showed that the mRNA expression of BIRC5, SHCBP1, CCNA2, SKA3 and GINS1 in LUAD and LUSC tissues were all significantly higher than that in normal tissues, whereas only BIRC5 and CCNA2 protein expression in lung cancer tissues were much higher than those in the normal lung tissues." (PMID 34806315, 2022). "In addition, compared with that of patients in the SHCBP1 low-expression group, the survival prognosis of LUAD patients in the SHCBP1 high-expression group who received radiotherapy was worse, indicating that lung cancer patients with low SHCBP1 expression are more sensitive to radiotherapy." (PMID 38365687, 2024).
non-small cell lung carcinoma (6 papers, 2020 to 2025). A group of at least three distinct histological types of lung cancer, including non-small cell squamous cell carcinoma, adenocarcinoma, and large cell carcinoma. "Interestingly, SHCBP1 also mediates EGF-induced activation of β-catenin signaling in non-small cell lung carcinoma (NSCLC) cells." (PMID 35013128, 2022). "Recent studies have demonstrated that the interaction between SHCBP1 and FGF13 could activate the AKT-GSK3α/β signaling pathway and consequently promote the proliferation of the non-small cell lung cancer (NSCLC) cell line A549." (PMID 38005336, 2023).
pancreatic cancer (6 papers, 2020 to 2025). "SHCBP1 knockdown significantly inhibits the proliferation and migration of pancreatic cancer cells in vitro." (PMID 40927361, 2025). "In breast and pancreatic cancer models, SHCBP1 knockout suppressed tumor progression in both 2D and 3D organoid systems and in patient-derived xenograft models." (PMID 41009347, 2025). "Overexpression of SHCBP1 promotes the proliferation, migration, and invasion of pancreatic cancer cells, while inhibition of SHCBP1 and EOGT inhibits these malignant processes in vitro." (PMID 35335147, 2022). "However, the exact role of SHCBP1 in pancreatic cancer stays unclear." (PMID 33291601, 2020). "Structure-based virtual screening using the AlphaFold-predicted SHCBP1 model identified AZD5582 as a potential SHCBP1-binding compound, which can suppress pancreatic cancer growth and metastasis through induction of apoptosis." (PMID 41009347, 2025). "Researchers have further elucidated the molecular mechanisms by which EOGT and SHCBP1 enhance the O-GlcNAcylation of NOTCH1, thus promoting the nuclear localization of NICD and inhibiting the transcription of E-cadherin and P21 in pancreatic cancer cells." (PMID 35335147, 2022).
prostate carcinoma (4 papers, 2022 to 2025). A carcinoma that arises from epithelial cells of the prostate gland. "In prostate cancer, SHCBP1 expression is strongly associated with key clinical variables, such as PSA titers, Gleason score, seminal vesicle invasion, and disease stage." (PMID 41009347, 2025). "In prostate cancer, SHCBP1 enhances cell proliferation and the G2/M transition via PLK1-mediated activation of CDC25C phosphorylation." (PMID 41009347, 2025). "SHCBP1 was found to enhance prostate cancer cell development, metastasis, and mitosis, with the SHCBP1—polo‐like kinase 1 (PLK1)—CDC25C axis playing a key role in promoting tumorigenesis." (PMID 39949984, 2025). "In the SHCBP1 knockdown group, the size and number of lesions, bone destruction, and invasiveness of prostate cancer bone metastases in mice were lower than those in the control group." (PMID 39949984, 2025). "Whole transcriptome sequencing of prostate cancer samples was conducted to identify oncogene expression, specifically focusing on SHCBP1." (PMID 39949984, 2025). "This study aimed to investigate the role of SHC protein SH2 structural domain binding protein 1 (SHCBP1) in prostate cancer bone metastasis." (PMID 39949984, 2025). "Clinical data showed elevated SHCBP1 expression in advanced prostate cancer stages." (PMID 39949984, 2025). "We therefore explored the effect of SHCBP1 on the EMT process of prostate cancer cells." (PMID 39949984, 2025). "Furthermore, SHCBP1 was significantly upregulated in prostate cancer tissues compared with BPH tissues." (PMID 35013128, 2022).
melanoma (3 papers, 2014 to 2023). A malignant, usually aggressive tumor composed of atypical, neoplastic melanocytes. "To further study the effect of SHCBP1 on the occurrence and development of melanoma, we first analyzed the expression of SHCBP1 in normal cells and melanoma cells." (PMID 38005336, 2023). "The expression of SHCBP1 in mouse melanoma B16 cells was significantly higher than that in MMPC cells." (PMID 38005336, 2023). "This means that SHCBP1 is actively involved in the development and progression of melanoma." (PMID 38005336, 2023). "Similarly, our study also found that SHCBP1 was highly expressed in melanoma B16 cells." (PMID 38005336, 2023). "However, whether SHCBP1 is involved in the regulation of the occurrence and development of melanoma remains unknown." (PMID 38005336, 2023). "In this study, we found that SHCBP1, as an important protein upstream of the ERK1/2 signaling pathway, may participate in the process of resveratrol-mediated inhibition of the proliferation of mouse melanoma B16 cells." (PMID 38005336, 2023). "Similarly, DEPDC1B SHCBP1, RRM2, PLK1, and UHRF1 have been found to promote melanoma proliferation and could be potential targets for treatment; their coefficients were all positive, which implies that they had an additive effect on the risk scores." (PMID 34384498, 2021). "However, the function of SHCBP1 in melanoma cells has not been fully elucidated." (PMID 38005336, 2023).
breast tumor (2 papers, 2022 to 2025). "Interestingly, both SHCBP1 and ORC6 also showed elevated expression in breast tumor samples compared to control samples in TCGA studies (FC = 7.42 and 5.48, respectively)." (PMID 35886011, 2022).
esophagogastric junction adenocarcinoma (2 papers, 2025). "USP49 drives malignant progression of esophagogastric junction adenocarcinoma by activating the SHC binding and spindle associated 1 (SHCBP1)/β-catenin/glutathione peroxidase 4 (GPX4) signaling pathway." (PMID 41035649, 2025).
Fanconi anemia (2 papers, 2023 to 2024). Fanconi anemia (FA) is a hereditary DNA repair disorder characterized by progressive pancytopenia with bone marrow failure, variable congenital malformations and predisposition to develop hematological or solid tumors.
head and neck squamous cell carcinoma (2 papers, 2025). A squamous cell carcinoma that arises from any of the following anatomic sites: lip and oral cavity, nasal cavity, paranasal sinuses, pharynx, larynx, and salivary glands. "In head and neck squamous cell carcinoma (HNSCC), SHCBP1 cooperates with KIF23 to regulate cell-cycle progression through several oncogenic signaling pathways." (PMID 40799237, 2025). "Furthermore, the interaction between SHCBP1 and KIF23 plays functional roles in modulating the cell cycle and cisplatin resistance in head and neck squamous cell carcinoma." (PMID 40789837, 2025).
skin cancer (2 papers, 2022 to 2023). "In a recent study, OA was shown to decrease the inflammatory factors and hyperplasia via the suppression of NF-κB signaling and SHC SH2 domain-binding protein 1 (SHCBP1) in skin cancer in vitro and in vivo models." (PMID 36139025, 2022).
autoimmune disease (1 paper, 2014). A disorder resulting from loss of function or tissue destruction of an organ or multiple organs, arising from humoral or cellular immune responses of the individual to their own tissue constituents. "Given the expression of Shcbp1 in inflammatory lesions within the spinal cord as well as reduced disease severity in Shcbp1 deficient mice, Shcbp1 may represent a therapeutic target for autoimmune disease such as multiple sclerosis." (PMID 25153088, 2014). "In this report, by generating mouse strains with conditional and global deletion of Shcbp1, we have carefully evaluated the in vivo requirement for Shcbp1 in T cell development as well as in an autoimmune disease model." (PMID 25153088, 2014). "To test whether Shcbp1 might play a role in vivo in T cell effector responses in the context of autoimmune disease, we chose to use the CD4 T cell driven experimental autoimmune encephalomyelitis (EAE) model." (PMID 25153088, 2014).
cervical cancer (1 paper, 2025). A primary or metastatic malignant neoplasm involving the cervix. "Functional loss studies using shRNA against SHCBP1 indicate EIF5A-dependent NF-κB activation is necessary for cervical cancer cell proliferation and self-renewal." (PMID 41009347, 2025). "In cervical cancer, SHCBP1 critically contributes to the cancer stem cell-like phenotype by regulating the expression of stemness-linked genes such as CD44, CD133, NANOG, and OCT4." (PMID 41009347, 2025).
cervical squamous cell carcinoma (1 paper, 2023). A squamous cell carcinoma arising from the cervical epithelium. "In addition, SHCBP1 expression was elevated (P<0.01) in cervical squamous cell carcinoma, endocervical adenocarcinoma (CESC), and pheochromocytoma (P<0.01)." (PMID 36920183, 2023).
cholangiocarcinoma (1 paper, 2017). A carcinoma that arises from the intrahepatic biliary tree (intrahepatic cholangiocarcinoma) or from the junction, or adjacent to the junction, of the right and left hepatic ducts (hilar cholangiocarcinoma). "The analysis of samples in our cohort also showed that the degree of downregulation of the miR-204 and of some of its targets (SHCBP1, CENPA, RAD51) was higher in the intrahepatic cholangiocarcinoma samples as opposed to the extrahepatic ones." (PMID 28199974, 2017).
colorectal cancer (1 paper, 2023). A primary or metastatic malignant neoplasm that affects the colon or rectum. "Moreover, our experimental results verified that SHCBP1 expression was upregulated in the liver, gastric, and colorectal cancer cell lines, which was consistent with public database information." (PMID 36920183, 2023).
esophageal carcinomas (1 paper, 2019). A primary or metastatic malignant neoplasm involving the esophagus. "Interestingly, the findings that nuclear translocation of SHCBP1 by EGF was also observed in cancer cell lines derived from liver, breast, and esophageal carcinomas, suggesting a possible generalizability of this biological event among different types of cancers." (PMID 30177836, 2019).
experimental autoimmune encephalomyelitis (1 paper, 2014). An autoimmune demyelinating disease of the central nervous system that is produced experimentally in animals by the injection of homogenized brain or spinal cord in Freund's adjuvant. "However, in a mouse model of experimental autoimmune encephalomyelitis (EAE), which depends on CD4+ T cell function and mimics multiple features of the human disease multiple sclerosis, Shcbp1 deficient mice had reduced disease severity and improved survival, and this effect was T cell intrinsic." (PMID 25153088, 2014).
glioblastoma (1 paper, 2025). The most malignant astrocytic tumor (WHO grade IV). "For instance, elevated SHCBP1 expression is observed in glioblastoma when compared to normal brain tissues and is linked to poorer overall survival rates in patients." (PMID 41009347, 2025).
lentivirus infection (1 paper, 2016). Virus diseases caused by the Lentivirus genus. "Annexin V-APC staining by FACS on HS-SY-II cells following lentivirus infection was further utilized to confirm the influence of SHCBP1 on cell apoptosis." (PMID 27572315, 2016).
liver cirrhosis (1 paper, 2025). "Furthermore, in liver cirrhosis patients, a positive correlation was observed between the expression of MCM7 or SHCBP1 mRNA and increased IL11 expression." (PMID 40789837, 2025).
liver fibrosis (1 paper, 2025). "qRT-PCR and Western blot analyses showed a significant upregulation of SHCBP1 expression in liver fibrosis in both patients and mouse models." (PMID 40789837, 2025). "In conclusion, our findings indicate that SHCBP1 is significantly upregulated in liver fibrosis and correlates with increased MCM7 expression." (PMID 40789837, 2025). "Conversely, in hepatocyte-specific SHCBP1 overexpression liver fibrosis models, we observed contrasting results." (PMID 40789837, 2025). "Collectively, these findings demonstrate that hepatocyte-derived SHCBP1 promotes liver fibrosis progression in mice." (PMID 40789837, 2025). "The upregulation of SHCBP1 mRNA and protein expression was also confirmed in primary hepatocytes isolated from liver fibrosis models." (PMID 40789837, 2025). "Given the critical role of MCM7 in liver fibrosis pathogenesis and its interaction with SHCBP1, we analyzed gene expression datasets (GSE61376, GSE25713, and GSE55747) and our RNA-seq data from S. japonicum- and CCl4-induced liver fibrosis models." (PMID 40789837, 2025). "Additionally, we found that increased hepatic SHCBP1 mRNA expression is significantly correlated with elevated MCM7 mRNA levels in liver fibrosis." (PMID 40789837, 2025). "Mechanistically, our findings demonstrated that MCM7 activates IL11 expression via the SHCBP1-RACGAP1-STAT3 signaling pathway, thereby promoting the hepatic stellate cell activation and driving liver fibrosis progression." (PMID 40789837, 2025). "To investigate the function of SHCBP1 in liver fibrosis, we constructed an AAV8 vector to knock down SHCBP1 in hepatocytes of liver fibrosis models." (PMID 40789837, 2025). "This interaction between MCM7 and SHCBP1 regulates IL11 expression through the RACGAP1-STAT3 pathway, underscoring a novel mechanism for liver fibrosis progression." (PMID 40789837, 2025). "Among these, SHCBP1 emerged as a key candidate, acting as a SHC SH2-domain binding protein that regulates multiple signaling pathways, including FGF, NF-κB, MAPK/ERK, PI3K/AKT, TGF-β1/Smad, and Wnt/β-catenin, suggesting its crucial and consistent role in liver fibrosis pathogenesis." (PMID 40789837, 2025).
lung adenocarcinoma (1 paper, 2025). A carcinoma that arises from the lung and is characterized by the presence of malignant glandular epithelial cells. "Rucaparib decreased cell proliferation and metastatic potential in lung adenocarcinoma cells by inhibiting SHCBP1 at the transcriptional level." (PMID 41009347, 2025). "Transcriptomic studies in lung adenocarcinoma have classified SHCBP1 within a mitochondrial quality-related gene (MORG) signature, where its high expression is linked to unfavorable prognosis and possible disruptions in mitochondrial homeostasis." (PMID 41009347, 2025). "SHCBP1 in lung adenocarcinoma is significantly upregulated in metastatic lesions, showing a strong association with unfavorable drug response and reduced overall survival among patients." (PMID 41009347, 2025).
lung squamous cell carcinoma (1 paper, 2022). "The mRNA expression of BIRC5, SHCBP1, CCNA2, SKA3, and GINS1 in LUAD and lung squamous cell carcinoma (LUSC) tissues were all significantly higher than that in normal tissues." (PMID 34806315, 2022).
lymphoma (1 paper, 2014). A malignant (clonal) proliferation of B- lymphocytes or T- lymphocytes which involves the lymph nodes, bone marrow and/or extranodal sites. "Microarray data have also suggested upregulation of SHCBP1 in certain leukemia/lymphoma in both humans and mice." (PMID 25153088, 2014). "Thus, the correlation between Shcbp1 and proliferation is potentially relevant for these lymphomas." (PMID 25153088, 2014).
measles (1 paper, 2014). A highly contagious viral infection caused by the measles virus. "Such conservation suggests that other viruses in the measles/Nipah groups may also bind SHCBP1 to block the viral polymerase." (PMID 24587180, 2014).
metastatic tumors (1 paper, 2025). "Moreover, SHCBP1 had a relatively higher expression in metastatic tumors than in primary tumors." (PMID 40799237, 2025).
multiple sclerosis (1 paper, 2014). A progressive autoimmune disorder affecting the central nervous system resulting in demyelination. "Interestingly, we found that Shcbp1 plays a role in CD4+ T cells in the context of the autoimmune EAE model of multiple sclerosis." (PMID 25153088, 2014). "Therefore, conditions that are present and therapeutically relevant in multiple sclerosis and EAE were capable of inducing Shcbp1 expression in CD4+ T cells ex vivo." (PMID 25153088, 2014).
Obesity (1 paper, 2025). Accumulation of substantial excess body fat. "The PTSD hubs, SHCBP1 and TTF1, were predicted to indirectly receive signals from the regulatory signatures of obesity and smoking." (PMID 40102990, 2025).